ZNF597 (zinc finger protein 597)
Description:
May be involved in transcriptional regulation.
Synonyms: FLJ33071; HIT-4
Tractability: PROTAC: UniProt records ubiquitination sites on it; ubiquitination databases record sites on it.
Gene: Protein-coding gene on chromosome 16 (3,432,414 to 3,443,504, reverse strand). Ensembl gene ENSG00000167981.
Subcellular location: Nucleus
Subcellular location (Human Protein Atlas): Nucleoli; Nucleoplasm
Pathways (Reactome):
Gene expression (Transcription): Generic Transcription Pathway
Gene Ontology:
Molecular function: protein binding; sequence-specific double-stranded DNA binding; DNA-binding transcription activator activity, RNA polymerase II-specific; RNA polymerase II cis-regulatory region sequence-specific DNA binding
Biological process: regulation of transcription by RNA polymerase II; positive regulation of transcription by RNA polymerase II; regulation of DNA-templated transcription
Cellular component: nucleus
Genetic constraint (gnomAD): Loss-of-function variants: 4 observed, 5.8 expected, observed/expected ratio (o/e) 0.69, 90% interval 0.34 to 1.53. That is too few expected variants to judge how well the gene tolerates losing a copy. Missense variants: 527 observed, 498.57 expected, observed/expected ratio (o/e) 1.06, 90% interval 0.98 to 1.14. Synonymous variants: 191 observed, 177.25 expected, observed/expected ratio (o/e) 1.08, 90% interval 0.96 to 1.22.
Homologues: Orthologues: chimpanzee ZNF597 (98% identical), macaque ZNF597 (94% identical), rabbit ZNF597 (72% identical), guinea pig ZNF597 (69% identical), dog ZNF597 (67% identical), mouse Zfp597 (62% identical), rat Zfp597 (61% identical), zebrafish prdm2a (16% identical), Caenorhabditis elegans ehn-3 (15% identical), Caenorhabditis elegans ztf-16 (15% identical), Caenorhabditis elegans sdz-12 (13% identical), Drosophila melanogaster CG12769 (10% identical). Paralogues in human: ZNF211 (29% identical), ZNF445 (29% identical), ZNF786 (28% identical), ZNF462 (19% identical), ZNF521 (18% identical), ZNF423 (18% identical), ZBTB39 (16% identical).
Diseases named in the same sentence as ZNF597 in open-access papers:
ZNF597 is named in the same sentence as 5 diseases in open-access papers, as found by Europe PMC text mining. Sharing a sentence is not in itself a finding about the gene and the disease. The quoted sentences say what the papers report.
osteosarcoma (2 papers, 2022 to 2023). A usually aggressive malignant bone-forming mesenchymal neoplasm, predominantly affecting adolescents and young adults. "The Kaplan–Meier survival analysis suggested that lower expressions of ATMIN, ZNF438, and ZNF597 and the higher expression of ZNF692 were associated with worse overall survival in osteosarcoma." (PMID 35281811, 2022). "It has been reported that ZNF597 (Zinc Finger Protein 597) may be a protective factor in osteosarcoma, but its role in cancer pathology remains unclear." (PMID 37958393, 2023).
breast carcinoma (1 paper, 2018). "ZNF597 is further validated to have lower expression in TCGA basal patients compared with other breast cancer subtype patients." (PMID 29458327, 2018).
cancer (3 papers, 2017 to 2023). A tumor composed of atypical neoplastic, often pleomorphic cells that invade other tissues. "The most frequently epimutated regions varied depending on tissue origin, with the maternally methylated ZNF597 DMR being affected in 66.6% of hepatocarcinoma cell lines, H19 in 28.9 % of lung, ZNF331 DMR1 in 32% of colon and GRB10 in 44.9% of breast-derived cancer cell lines." (PMID 28883545, 2017).
ZNF597 also shares sentences with these, for which no sentence is quoted: tumor (2 papers); infection (1).